NAV2 (neuron navigator 2)
Description:
Possesses 3' to 5' helicase activity and exonuclease activity. Involved in cytoskeleton organization. Required for neurite outgrowth in response to stimulation by all-trans retinoic acid (atRA). Involved in neuronal development, specifically in the development of different sensory organs. Important for brain and cerebellar development. Involved in the differentiation, migration and axonal extension of granule cells in the developing cerebellum (By similarity). Involved in the development of the glossopharyngeal cranial nerve IX and the vagus cranial nerve X, possibly by influencing neuronal cell elongation or survival; influencing the efficiency of the baroreceptor reflex response to changes in blood pressure (By similarity).
Synonyms: unc53H2; HELAD1; KIAA1419; POMFIL2; RAINB1; STEERIN2; FLJ10633; FLJ11030; FLJ23707
Tractability: Antibody: its Gene Ontology location is reachable by antibodies, with medium confidence. PROTAC: ubiquitination databases record sites on it; its protein half-life has been measured.
Gene: Protein-coding gene on chromosome 11 (19,350,724 to 20,121,601, forward strand). Ensembl gene ENSG00000166833.
Subcellular location: Nucleus; Cytoplasm, cytoskeleton; Cell projection, axon; Perikaryon
Subcellular location (Human Protein Atlas): Nucleoplasm
Gene Ontology:
Molecular function: 3'-5' DNA helicase activity; ATP hydrolysis activity; protein binding; DNA helicase activity
Biological process: nervous system development; cerebellar cortex development; neurogenesis
Cellular component: nucleoplasm; nucleus; perikaryon; axon; cytoskeleton
Genetic constraint (gnomAD): Loss-of-function variants: 48 observed, 211.95 expected, observed/expected ratio (o/e) 0.23, 90% interval 0.18 to 0.29. The upper end of that interval is the gene's LOEUF score, 0.29, which puts it in group 1 of 6, group 1 being the genes least tolerant of losing a copy. Missense variants: 2,666 observed, 3,123.2 expected, observed/expected ratio (o/e) 0.85, 90% interval 0.83 to 0.88. Synonymous variants: 1,231 observed, 1,237.4 expected, observed/expected ratio (o/e) 0.99, 90% interval 0.95 to 1.04.
Homologues: Orthologues: chimpanzee NAV2 (99% identical), macaque NAV2 (99% identical), dog NAV2 (96% identical), pig NAV2 (95% identical), rabbit NAV2 (93% identical), rat Nav2 (93% identical), mouse Nav2 (90% identical), guinea pig NAV2 (89% identical), tropical clawed frog nav2 (77% identical), zebrafish nav2a (64% identical), zebrafish nav2b (55% identical), Caenorhabditis elegans unc-53 (19% identical). Paralogues in human: NAV3 (55% identical), NAV1 (34% identical).
Diseases named in the same sentence as NAV2 in open-access papers:
NAV2 is named in the same sentence as 44 diseases in open-access papers, as found by Europe PMC text mining. Sharing a sentence is not in itself a finding about the gene and the disease. The quoted sentences say what the papers report.
neuroblastoma (5 papers, 2011 to 2023). Neuroblastoma (NB) is the most common solid, extracranial childhood tumor. "Nav2 mRNA expression is induced in SH-SY5Y human neuroblastoma cells after all-trans retinoic acid (atRA) treatment." (PMID 36710926, 2022). "Some of the top 20 genes found in this search are for example, neuron navigator 2 isoform 3 (NAV2), which is required for all-trans retinoic acid to induce neurite outgrowth in human neuroblastoma cells." (PMID 29914355, 2018). "Recently, a number of genes including neuron navigator 2 (Nav2) and Nedd9 were discovered in a screen for RA-responsive genes in a neuroblastoma cell line that elaborates neurites in response to RA." (PMID 22254103, 2011). "Finally, the third target was a G4 located downstream of exon 16 in NAV2 (navigator protein 2), which is required for retinoic acid-induced neurite outgrowth in human neuroblastoma cells." (PMID 35504902, 2022). "Nav2 is necessary for neuritogenesis in neuron-like SH-SY5Y cells, and Nav1 is necessary for neuritogenesis in multiple systems, including neuroblastoma cells and primary hippocampal neurons." (PMID 36710926, 2022). "When NAV2 is knocked down, the neuroblastoma cell is no longer able to extend neurites in response to RA." (PMID 22254103, 2011).
rheumatoid arthritis (5 papers, 2023 to 2025). A chronic, systemic autoimmune disorder characterized by inflammation in the synovial membranes and articular surfaces. "NAV2 is broadly expressed across tissues, including the small and large intestines and exhibits pleiotropic functions, but is implicated in colorectal cancer and rheumatoid arthritis, suggesting an immunomodulatory connection." (PMID 40892706, 2025). "Collectively, these multi-level and multi-dimensional findings strongly confirm that MAT exerts its therapeutic efficacy on the rheumatoid arthritis animal model through suppression of the NAV2-Wnt3a-β-catenin signaling cascade." (PMID 40936889, 2025). "In particular, it has beenshown that the NAV2 protein promotes the inflammatoryresponse of fibrocyte-like synoviocytes by activating the Wntsignaling pathway in rheumatoid arthritis, and its inhibitioncan reduce joint inflammation in this disease." (PMID 41536794, 2025). "Wang R., Li M., Wu W., Qiu Y., Hu W., Li Z., Wang Z., Yu Y., Liao J.,Sun W., Mao J., Zhu Y.Z. NAV2 positively modulates inflammatoryresponse through Wnt/β-catenin signaling in rheumatoid arthritis.Clin Transl Med." (PMID 41536794, 2025). "NAV2 positively modulates inflammatory response of fibroblast-like synoviocytes through activating Wnt/β-catenin signalling pathway in rheumatoid arthritis, which is also an important pathway in chondrocyte biology." (PMID 38152138, 2023). "Collectively, these observations strongly suggest that NAV2 may serve as a novel molecular mediator in the treatment of rheumatoid arthritis." (PMID 40936889, 2025).
colorectal cancer (4 papers, 2015 to 2025). A primary or metastatic malignant neoplasm that affects the colon or rectum. "In particular, Nav2 was shown to promote invasion of colorectal cancer cells." (PMID 36710926, 2022). "However, the prognostic value of NAV2 expression in colorectal cancer (CRC) patients and the potential pathway through which NAV2 promotes migration and invasion in CRC cell lines is poorly understood." (PMID 26452645, 2015).
asthma (3 papers, 2017 to 2021). "NAV2 is critical to vagus nerve development, is associated with gut microbiome composition, and was previously associated with placebo response in asthma." (PMID 35295415, 2021).
autism (3 papers, 2020 to 2026). Persistent deficits in social interaction and communication and interaction as well as a markedly restricted repertoire of activity and interest as well as repetitive patterns of behavior. "When we expanded the dataset to include the entire 271 autism susceptibility genes that are expressed in the human amygdala, we found an additional five genes (PHF21A, RNABP17, ELP4, CNKSR2, and NAV2) with altered expression in individuals with ASD." (PMID 32460837, 2020).
colon cancer (2 papers, 2015 to 2022). "Studies on other genes belonging to the same family (NAV2 and NAV3) showed their opposed roles in colon cancer development." (PMID 35867729, 2022). "Previous studies have highlighted that NAV2 was abundantly expressed in 16 of 20 colon cancers examined but hardly detectable in corresponding non-cancerous mucosae using semi-quantitative RT-PCR, NAV2 showed 3’ to 5’ helicase activity and exonuclease activity in vitro as an oncogene." (PMID 26452645, 2015).
epilepsy (2 papers, 2023 to 2024). A brain disorder characterized by episodes of abnormally increased neuronal discharge resulting in transient episodes of sensory or motor neurological dysfunction, or psychic dysfunction. "Nav2, Ptpn5, Ldha, and Dbx1 are deemed higher priority as they have a direct biological association with seizures or epilepsy, while Prmt3 and Slc6a5 have an indirect association." (PMID 38862622, 2024). "Further reports of affected subjects will elucidate whether epilepsy may be part of the NAV2-related phenotypic spectrum." (PMID 35218524, 2023).
Tinnitus (2 papers, 2022 to 2024). Tinnitus is an auditory perception that can be described as the experience of sound, in the ear or in the head, in the absence of external acoustic stimulation. "The identification of genes such as CACNA1E or NAV2, showing enrichment of missense and large structural variants in patients with tinnitus may lead to defining new druggable targets for tinnitus." (PMID 38334885, 2024). "Interestingly, the NAV2 gene was found enriched in missense variants in patients with severe tinnitus, and this enrichment was successfully replicated in the JAGUAR cohort." (PMID 36450758, 2022). "In this study, we report a burden of missense and LSV in constraint regions and support CACNA1E, NAV2, and TMEM132D as new candidate genes that contribute to severe tinnitus." (PMID 36450758, 2022).
acute lymphoblastic leukemia (1 paper, 2022). Leukemia with an acute onset, characterized by the presence of lymphoblasts in the bone marrow and the peripheral blood. "Two replicated CpGs, located on genes NAV2 and CAMK2B, had been related to childhood acute lymphoblastic leukemia in a previous study." (PMID 36266660, 2022).
Alzheimer disease (1 paper, 2022). A progressive, neurodegenerative disease characterized by loss of function and death of nerve cells in several areas of the brain leading to loss of cognitive function such as memory and language. "Interestingly, multiple single-nucleotide polymorphisms in the NAV2 gene have been associated with Alzheimer’s Disease risk and age of onset." (PMID 36710926, 2022). "While more research needs to be done to confirm the involvement of Nav2 in Alzheimer’s Disease, these studies highlight the potential of Nav2 to contribute to neurodevelopmental and neurodegenerative disease." (PMID 36710926, 2022).
Ataxia (1 paper, 2023). Ataxia refers to impaired coordination of voluntary muscle movement. "The critical role of NAV2 in neuronal migration and axon elongation has also been observed in the hypomorphic Nav2 mutant mice that display ataxia due to defects in the development of cerebellar vermis, characterized by reduced cerebellar granule cell migration and impaired axonal outgrowth." (PMID 35218524, 2023). "Indeed, hypomorphic mutant mice lacking the full-length Nav2 transcript exhibit ataxia with reduced volume and abnormal foliation of the vermis mostly affecting folia VI-VII." (PMID 35218524, 2023).
Cerebellar hypoplasia (1 paper, 2023). Cerebellar hypoplasia is a descriptive term implying a cerebellum with a reduced volume, but a normal shape and is stable over time. "Stepwise filtering of ES analysis retained two compound heterozygous variants in NAV2 (NM_001244963.2): c.5179_5180delAG, p.(Leu1728Trpfs*2) and c.6757delA,p.(Ile2253*) in a female with developmental delay and a diagnosis of cerebellar hypoplasia and dysplasia." (PMID 35218524, 2023).
cortical dysplasia (1 paper, 2023). "In this study, we report biallelic truncating variants in NAV2 associated with a novel human neurodevelopmental phenotype characterized by vermis hypoplasia and cerebellar cortical dysplasia as well as other brain malformation." (PMID 35218524, 2023).
cutaneous melanoma (1 paper, 2022). A primary melanoma arising from atypical melanocytes in the skin. "Moreover, inhibition of GSK3β, which increased β-catenin and SNAIL activity, contributed to the invasion of NAV2-associated cutaneous melanoma cells." (PMID 35350242, 2022).
developmental delay (1 paper, 2023). "This led to the identification of compound heterozygous truncating variants in NAV2 in a female individual affected with developmental delay and a complex brain malformation including vermian hypoplasia and cerebellar cortical dysplasia." (PMID 35218524, 2023).
endometrial stromal sarcomas (1 paper, 2023). "Uterine leiomyosarcomas have been shown to overexpress NAV2 when compared to endometrial stromal sarcomas, and it has been proposed as a candidate prognostic marker in uterine leiomyosarcoma." (PMID 37789421, 2023).
endometriosis (1 paper, 2023). The growth of functional endometrial tissue in anatomic sites outside the uterine body. "Segregating variants in FGFR4, NALCN, and NAV2 were screened in 92 individuals with endometriosis and in 19 individuals with both endometriosis and an associated tumor." (PMID 37789421, 2023). "Here, we provide FGFR4, NALCN, and NAV2 as novel high-risk candidate genes for familial endometriosis." (PMID 37789421, 2023).
Hepatitis (1 paper, 2023). Inflammation of the liver. "The mutation rate of the NAV2 gene was 8.6% (31/360) in TCGA–Liver Hepatocellular Carcinoma (LIHC) data, and the NAV2 gene was reported to be associated with hepatitis but not HCC." (PMID 38003606, 2023).
hyperlipidemia (1 paper, 2021). "It was reported that NAV2 was associated with hyperlipidemia." (PMID 34675963, 2021).
memory impairment (1 paper, 2015). "Two genes are consistently associated with all seven memory scores: neuron navigator 2 (NAV2) and Translocase Of Outer Mitochondrial Membrane 40 Homolog (TOMM40), where TOMM40 is proximal to APOE and has been reported to be associated with the memory impairment." (PMID 25859259, 2015).
metastatic tumor (1 paper, 2015). "In addition, we found that NAV2 mRNA (paired t-test, p = 0.0142) and protein (paired t-test, p = 0.0043) expression in metastatic tumor tissue were higher than in paired primary tumor tissue." (PMID 26452645, 2015).
neuritis (1 paper, 2024). A neuropathy arising from inflammation of one or more nerves. "Nav2 is very highly expressed in the developing mice brain and functions in the neurite outgrowth, axonal elongation, interaction with microtubules and neurofilaments that are key players in the formation and stability of growing neuritis." (PMID 39038237, 2024).
neuronal migration disorder (1 paper, 2022). "Indeed, Nav2 hypomorphic mutant mice have a small corpus callosum (a major cortical axon tract), and a human patient with Nav2 mutations displayed cortical dysgyria (a neuronal migration disorder), as well as hypoplasia of the corpus callosum and anterior commissure, among other abnormalities." (PMID 36710926, 2022).
tumor (6 papers, 2015 to 2025). "One variant with a low allele frequency (AF 0.08, 3/39 reads) in NAV2 (c.2018C>T, p.(Ala673Val)) was identified in the tumor sample of II-2." (PMID 37789421, 2023). "Meanwhile, univariate and multivariate analysis indicated that high NAV2 expression combined with high tumor budding grade is associated with shorter RFS and OS than other combinations with a different status of the two factors." (PMID 26452645, 2015). "The immunofluorescence results showed that loss of expression of NAV2 could regulate F-actin depolymerization, which plays an essential role in tumor migration and invasion." (PMID 26452645, 2015). "NAV2, as a member of the neuron navigator (NAV) protein family, has been implicated in tumor invasion, as well as lymph node and distant metastasis." (PMID 40936889, 2025). "NAV2 also regulates the cytoskeleton, which affects cell-cell and cell-matrix adhesion, facilitating tumor cell invasion and metastasis." (PMID 26452645, 2015). "Furthermore, Cox regression analysis revealed that high NAV2 expression integrated with high tumor budding grade was a powerful independent predictive factor of CRC clinical outcome." (PMID 26452645, 2015). "In sum, NAV2 may promote tumor budding generation, but the specific mechanisms require further research." (PMID 26452645, 2015). "In summary, NAV2 and tumor budding were independent prognostic factors that could affected RFS and OS of CRC patients." (PMID 26452645, 2015). "However, so far, the mechanism by which NAV2 promotes tumor cell invasion and metastasis remains unclear, and further studies are needed to elucidate this." (PMID 26452645, 2015). "Meanwhile, AAA+ protein family members, which share homology with one of NAV2 functional protein domains, have also been shown to have increased expression in CRC tumor budding." (PMID 26452645, 2015). "NAV2 was deemed to be one of target genes of APC/Wnt/β-catenin, which is a signaling pathway that plays an essential role in tumor progression according to studies using the CRC cell line SW480." (PMID 26452645, 2015). "When analyzing the levels of NAV2 expression in CRC tissues by immunohisto chemistry, we found an interesting phenomenon that high NAV2 expression was accompanied by a high tumor budding grade." (PMID 26452645, 2015). "At the same time, NAV2 activated the SSH1L/cofilin-1 pathway and facilitated tumor cell migration and invasion through F-actin polymerization." (PMID 26452645, 2015). "According to our findings, NAV2 was overexpressed in high tumor budding grade CRC samples, and its expression level was positively correlated with tumor budding grade." (PMID 26452645, 2015). "Furthermore, our data demonstrate that NAV2 promotes CRC invasion and metastasis by regulating F-actin polymerization via the SSH1L/cofilin-1 pathway and boosting tumor budding generation in terms of pathologic morphology." (PMID 26452645, 2015). "The result showed that NAV2 was more highly expressed in strong metastatic potency cell lines than weak metastatic potency cell lines, and the expression level of metastatic cell line SW460 was higher than that of primary tumor cell line SW480." (PMID 26452645, 2015). "The result of the analysis showed that high tumor budding grade ahead of the invasive front was positively correlated with late TNM stage (Spearman’s correlation, r = 0.3760, p < 0.0001) and high expression level of NAV2 (Spearman’s correlation, r = 0.6208, p < 0.0001)." (PMID 26452645, 2015).
cancer (3 papers, 2015 to 2022). A tumor composed of atypical neoplastic, often pleomorphic cells that invade other tissues. "In vitro and in vivo assays demonstrated that knockdown of NAV2 led to reduced migration and invasion of cancer cells, and the process involved the regulation of F-actin polymerization through the SSH1L/cofilin-1 pathway." (PMID 26452645, 2015).
neurodevelopmental disorder (3 papers, 2022 to 2024). A behavioral and cognitive disorder with onset during the developmental period that involves impaired or aberrant development of intellectual, motor, or social functions. "Bi-allelic loss-of-function of NAV2 was reported to cause a neurodevelopmental disorder with a complex brain malformation." (PMID 38862622, 2024). "In summary, our results unveil a novel human neurodevelopmental disorder due to genetic loss of NAV2, highlighting a critical conserved role of the NAV2 gene in brain and cerebellar development across species." (PMID 35218524, 2023). "The recent identification of a patient with a neurodevelopmental disorder attributable to the loss of Nav2 underscores the urgency to characterize the molecules and the cellular processes in which the Navigators participate, which will further our understanding of human health and disease." (PMID 36710926, 2022).
NAV2 also shares sentences with these, for which no sentence is quoted: deafness (3 papers); Arthritis (2); melanoma (2); bipolar disorder (1); brain malformations (1); breast carcinoma (1); Cerebellar dysplasia (1); Dravet syndrome (1); glioma (1); hepatocellular carcinoma (1); Infertility (1); lung carcinoma (1); meningioma (1); neurodegenerative disease (1); neurological disorders (1); ovarian carcinoma (1); schizophrenia (1); tubulinopathies (1).